CD44 (CD44 molecule (IN blood group))
Diseases named in the same sentence as CD44 in open-access papers (continued):
Sharing a sentence is not in itself a finding about the gene and the disease.
gastric cancer (continued). "In addition, CPT1C promotes gastric cancer drug resistance by enhancing FAO and subsequently upregulating the mRNA expression levels of gastric cancer stem cell markers (CD44, EpCam, and Lgr5)." (PMID 41219902, 2025). "To determine whether CD44 expression was increased by NINJ2, we generated stable gastric cancer cells overexpressing (O/E) NINJ2 isoform-1 and -3." (PMID 40518514, 2025). "The molecular mechanism behind this effect involved the increased expression of CD44, a cancer stem cell marker in numerous human solid tumors, and subsequent upregulation of asialoglycoprotein receptor 2 (ASGRA2), which acts as an oncogene in gastric cancer." (PMID 41154647, 2025). "CD44 and OCT4 are commonly used indicators of gastric cancer stem cells." (PMID 39247186, 2024). "Previous studies have shown that CD44v is the dominant form of CD44 in the human gastric cancer tissue, and more importantly, CD44v but not CD44s increased the frequency of tumor initiation in immunocompromised mice 48-50." (PMID 35864961, 2022). "The UALCAN database showed that CD44 was independent of sex in gastric cancer but correlated with cancer stage and lymph node metastasis." (PMID 36316684, 2022). "In addition, RA decreased the expression of CSC markers (CD44 and ALDH) and stemness genes (KLF4 and SOX2) and inhibited CSC properties such as tumorspheres formation in gastric cancer." (PMID 34400945, 2021). "Therefore, CD44, CD133, OCT4 and SOX2 are generally considered as the surface markers of gastric cancer stem cell." (PMID 32788883, 2020). "UWG02ASC displayed an almost identical phenotype to UWG02 CTC except for the gastric cancer stem cell marker CD44, which was strongly positive in UWG02CTC but negative in UWG02ASC." (PMID 31953491, 2020). "CD44s expression in CD44-negative gastric cancer cells with moderate HA secretion levels resulted in significant increase in cell-associated HA." (PMID 30909497, 2019). "The gastric cancer cell lines MKN-45 and SGC-7901 were cultured in CM from GCAFs for 72 h, and flow cytometry was performed to evaluate the percentage of CSC-like cells based on the expression of the cell surface markers CD44 and CD24." (PMID 31139014, 2019). "Moreover, patients with CD44- and CD133-positive gastric cancer were found to have a poorer survival rate than patients with CD44- and CD133-negative disease." (PMID 31619711, 2019). "To answer this question, we utilized CD44-negative human gastric carcinoma cell line MKN74 manipulated to stably express CD44 standard form (CD44s)." (PMID 30909497, 2019). "It was also reported that expression level of Hedgehog-related proteins was higher in gastric cancer stem cells expressing both CD44 and CD24 compared with non-expressing ones." (PMID 29642386, 2018). "In gastric cancer cell, GAPLINC has also been found to regulate CD44-dependent cell invasiveness." (PMID 30177521, 2018). "In this study, we aimed to analyze the effects of mtDNA content on cell surfacepositivity for anti-CD24 and anti-CD44 antibodies and chemoresistance level in AGS, HGC-27 and MKN-45 gastric cancer(GC) cell lines and to determine a setpoint for mtDNA copy for each cell line." (PMID 29845783, 2018). "In the present study, we identified and isolated CSC-like cells from the gastric cancer cell lines MKN45 and MKN74 by fluorescence-activated cell sorting (FACS) analysis of CD44 and an in vitro sphere formation assay, and targeted quiescent CSC-like cells in spheres." (PMID 28430578, 2017). "The expression of CD44 protein was present in patients with precancerous gastric lesions (21.4%) and gastric cancer (65%) but no patients with chronic gastritis were positive for CD44 staining." (PMID 29445738, 2017).
gastric cancer (continued). "Consequently, the expression of several β-catenin target genes decreases, including Axin2, Lgr5, Cd44, Birc5, and c-myc, indicating that CCAR1 functions in the same way in gastric cancer cells as it does in colon carcinoma cells." (PMID 28230774, 2017). "To clarify the role of Bmi-1 in stemness of gastric cancer, we checked the expression of Bmi-1 in microsphere and found that sphere cells from SGC7901 and MKN45 cell lines overexpressed Bmi-1 and other stem cell markers Oct-4, Sox2, Nanog, CD44, and CD133." (PMID 27644439, 2016). "Collectively, our findings indicate that SALL4 promotes gastric cancer progression through directly activating CD44 expression, which suggests a novel mechanism for the oncogenic roles of SALL4 in gastric cancer and represents a new target for gastric cancer therapy." (PMID 27819668, 2016). "The expression of CD44 and CD133 on hybrid cells was stronger than parental gastric cancer cells." (PMID 26498753, 2015). "Recent studies demonstrated that RHAMM- and CD44-mediated cell adhesion and motility appear reciprocal rather than overlapping, whereas concurrent expression of CD44 and RHAMM genes might confer tumorigenicity of gastric cancer cells." (PMID 25999946, 2015). "Multivariate regression analysis indicated that positive CD44 expression (P = 0.029), TNM staging (P < 0.001), and lymphovascular invasion (P = 0.016), but not CD24 expression (P = 0.065), were independent prognostic factors in gastric cancer." (PMID 25212506, 2014). "The present study simultaneously analyzed CD24 and CD44 expression levels independently and showed that positive expression of CD44 alone, but not CD24, was associated with poor survival in gastric carcinoma." (PMID 25212506, 2014). "A possible explanation is that IL-18 may have promoted gastric cancer cells migration and invasion via the regulation of CD70, CD44 and VEGF expression in immune cells, which deserves our further investigation." (PMID 24223129, 2013). "After adjusting for other risk factors, the association of CD44 expression (aOR = 0.66, 95% CI: 0.10-4.26, P = 0.658), CD24 expression (aOR = 0.09, 95% CI: 0.01-1.35, P = 0.081) or combined (CD44/CD24) with gastric cancer recurrence were not significant." (PMID 22839505, 2012). "In addition, recent reports indicate CD44, ADAM17 and another putative stem cell marker, Musashi-1 coexpresses with stem cell markers Lgr5 in both normal and gastric cancer patient tissues." (PMID 23217022, 2012). "Neither individual expression of CD24 or CD44, nor combined expression of CD44/CD24 was associated with recurrence of gastric carcinoma." (PMID 22839505, 2012). "Despite its presence on non-tumor cells, CD44 is commonly explored as a cancer-related biomarker since it is overexpressed on the cell surfaces of major cancers, such as pancreatic, breast, prostate, lung, and gastric cancer." (PMID 37754116, 2023). "In addition, pluripotency proteins are co-expressed by CD44+ cells, and OCT4 participates in self-renewal and chemoresistance and may represent the stemness of gastric cancer." (PMID 36838713, 2023). "In a cohort of 87 gastric cancer patients and a control group of 14 individuals, we analyzed the absolute RNA concentration from extracellular vesicles (EV) and the relative levels of FASN, PTEN, and CD44 mRNA, and their correlation with clinico-pathological features." (PMID 34885085, 2021). "As expected, both tumorsphere formation assay, CD44 expression detected by flow cytometry and stemness related markers (SOX-2, OCT-4, Nanog) detected by WB confirmed that miR-144-3p could attenuate the stemness of gastric cancer cells." (PMID 34657624, 2021). "Experimental evidence shows that the gastric cancer cell line 44As3 promotes asporin expression in CAFs via a mechanism in which, asporin as a unique class I SLRP, enhances the co-invasion of CAFs and cancer cells both in vitro and in vivo through the CD44/Rac1 mediated axis." (PMID 31608236, 2019).
gastric cancer (continued). "Conversely, previous reports have shown that EGFR directly interacts with CD44,32,33 although we could not reproduce this interaction in our gastric cancer PDCs (unpublished observations)." (PMID 31607750, 2019). "Therefore, from a molecular perspective, the asporin/CD44/EMT signaling pathway could be considered as a potential therapeutic target axis to decrease tumor migration and invasion in pancreatic and gastric cancer." (PMID 31608236, 2019). "However, the results of this work indicated that CD44 expression does not induce the total number of secreted EV of gastric cancer cells." (PMID 30909497, 2019). "However, CD44 expression did not have any effect on the total numbers of EV secreted by gastric cancer cells." (PMID 30909497, 2019). "Furthermore, there is lack of information about the corresponding of CD44 expression and the progression of gastric cancer in precancerous gastric lesions." (PMID 29445738, 2017). "Moreover, we also compared gastric cancer stem cells marker expression, such as OCT-4, Sox2, Nanog, Survivin and CD44, in tumor spheres and tumor spheres treated with ICG-001, which showed those markers were higher in tumor spheres than cell lines, but declined after ICG-001 treatment." (PMID 28893318, 2017). "HMGA2 could promote the gastric cancer cell motility and EMT via increasing CD44." (PMID 28968424, 2017). "Our results obtained by analyzing 162 gastric cancer patients and 125 chronic gastritis and 165 precancerous gastric lesions from three study centers showed that CD44 protein staining was positive in patients with precancerous (21.4%) and gastric cancer (65%) and negative with chronic gastritis." (PMID 29445738, 2017). "Interestingly, Lgr5 and CD44 are two known stem cell markers, suggesting that CCAR1 may also be important for the maintenance of gastric cancer stem cells." (PMID 28230774, 2017). "However, to the best of our knowledge, the correlation of CD44, Shh, and Gli1 in gastric cancer and their clinicopathological significance have not been reported in the literature." (PMID 26839535, 2016). "Taken together, it is apparent that CD44 maintains the stemness of gastric cancers, and it is not only a cell-surface marker, but also might be a driving factor in the development of CSCs." (PMID 26769843, 2016). "No influence of CD44 mRNA on mixed-type gastric cancer was found (P = 0.14)." (PMID 27323782, 2016). "However, after adjusting for other risk factors, the association of CD44 expression (aOR = 0.66, 95% CI: 0.10-4.26, P = 0.658) and CD24 expression (aOR = 0.09, 95% CI: 0.01-1.35, P = 0.081) with gastric cancer recurrence were still not significant." (PMID 22839505, 2012). "With a gene copy number of 4 or more defined as gene amplification, we found that ERBB4, C-MET and CD44 genes were frequently amplified in gastric cancers, however, other genes were not or infrequently amplified in gastric cancers, ranging from 0 to 8% (data not shown)." (PMID 22606006, 2012). "The clinical relevance of targeting CSC-associated genes is supported by several recent studies, including CD44 targeting for treatment of acute myeloid leukemia, CD24 targeting for treatment of colon and pancreatic cancer, and CD133 targeting for hepatocellular and gastric cancer." (PMID 21317983, 2011). "In gastric cancer tissues, Western blot revealed that the expression level of FTO and CD44 was significantly higher than that of adjacent tissues, and in immunohistochemistry, FTO expression was significantly elevated in GC patients, with positive staining mainly concentrated in GC cell nuclei." (PMID 36918410, 2023). "Since the related features do not overlap, combined detection of CD44 and CD133 expression can be an especially effective tool for pathological diagnosis and prognostic prediction of gastric cancer patients in clinical applications." (PMID 27759647, 2016).
gastric cancer (continued). "To further clarify the importance of SALL4-mediated upregulation of CD44 in gastric cancer growth in vivo, we implanted SALL4 knockdown cells with or without CD44 overexpression into the nude mice." (PMID 27819668, 2016). "Since adhesion molecules CD44 and CD24 do not appear to be clinically useful for prediction of gastric carcinoma recurrence after curative resection, future research is warranted to both confirm these results and to investigate other possible biomarkers." (PMID 22839505, 2012). "Since the related features do not overlap, combined detection of CD44 and CD133 expression could be an especially effective tool for diagnosis and treatment of patients with gastric cancer." (PMID 27759647, 2016). "Similarly, the other gastric cancer cell lines, such as MKN7, KATOIII, and NUGC3, expressed both CD44 and CD47 with different fluorescence intensities (data not shown)." (PMID 26077800, 2015). "Previously, gastric TICs have been identified by using CD44, CD44 and EpCAM, CD44 and CD24, CD44 and CD54, CD90, and aldehyde dehydrogenase 1 as markers, but CD49f has not been used to detect TICs in gastric cancers." (PMID 24015244, 2013). "However, no obvious trend was found among CD44, CD4, and CD74 mRNA in gastric cancer." (PMID 27323782, 2016).
colon carcinoma (354 papers, 1996 to 2025). "Recently, PIEZO1 was found to be highly expressed in the CD133 + CD44+ colon cancer tissue and associated with patients in the advanced clinical stage." (PMID 40890143, 2025). "Inactivation of DNMT1/3b in colon carcinoma cells induced a partial epithelial-mesenchymal transition associated with increased CD44 variant exon skipping." (PMID 38784389, 2024). "Piezo1high/CD133+CD44+ colon tumors are associated with advanced clinical stage, suggesting that the presence of Piezo1high/CD133+CD44+ CCSCs is a potential prognostic marker, and Piezo1 is a promising target for the selective elimination of CCSCs." (PMID 37306789, 2023). "SPP1 encoded osteopontin (OPN), the physiological ligand for CD44, acts as an immune checkpoint to suppress T cell activation and confers host tumor immune tolerance in human colon carcinoma that correlated with decreased patient survival." (PMID 35634447, 2022). "LoVo/DX cells highly overexpress the CD44 cell surface marker associated with colon cancer stemness." (PMID 35326523, 2022). "Colon cancer cells modify CD44 with O-linked glycosyl groups, blocking CD44-mediated adhesion to HA." (PMID 35936713, 2022). "Here, we found that HCT116 colon carcinoma cells inactivated for the DNA methylases DNMT1/3b undergo a partial epithelial to mesenchymal transition associated with increased CD44 variant exon skipping." (PMID 34086943, 2021). "ALDH1 is a common well-known marker for many types of tumors, while CD133 and CD44 are reported to be closely associated with both melanoma and colon carcinoma." (PMID 34055629, 2021). "Our future research will focus on evaluation of diagnostic potential of CD44 and its isoforms mainly CD44v8-10 for early diagnosis of colon precancerosis and risk prognosis of colon cancer." (PMID 34257584, 2021). "Taken together, these results indicate that PRDX2 expression is closely associated with CD133+CD44+ CCSCs in colon cancer." (PMID 33819194, 2021). "In colon cancer, CD44 overexpression is associated with mesenchymal phenotype and increased cell migration and invasion abilities, while CD44 knockdown decreases cell migration and invasion abilities." (PMID 34439211, 2021). "CD44 variant (CD44v, a CD44 isoform) expression in colon carcinoma cell lines reduced rolling velocity and increased binding to P‐selectin." (PMID 33210465, 2020). "For example, variant isoforms of CD44 are P‐selectin and l‐selectin ligands on colon carcinoma cells, possibly owing to O‐linked glycosylation." (PMID 29577645, 2018). "Consistently, qPCR analysis revealed that the expression of genes associated with colon cancer stem cells, including CD44, CD133, LGR5, and AXIN2, was reduced in SREBP1 and SREBP2 knockdown DLD1 and Pt130 cells." (PMID 29449559, 2018). "In colon cancer cells, a mesenchymal phenotype was associated with an increase in CD44 and knock-down of CD44 showed a decrease in EMT phenotype." (PMID 29747682, 2018). "Binding of PNA (peanut agglutinin) to a CD44 variant glycoprotein receptor in HT29 colon cancer cells, correlated with an increased metastatic potential." (PMID 28598369, 2017). "More importantly, variants of CD44, specifically CD44v6, promote tumor progression and metastatic potential in lung, breast, and colon cancer." (PMID 25999946, 2015). "In COADREAD, AKT isoforms (including AKT1) are associated with high expression of CD133 and CD44 (cancer stem cell markers) and radiation resistance in colon cancer cells." (PMID 26202601, 2015). "The cell surface proteins CD133, CD24 and CD44 are putative markers for cancer stem cell populations in colon cancer, associated with aggressive cancer types and poor prognosis." (PMID 24760019, 2014). "This study presents the association of CD133 and CD44 in terms of radiation resistance in colon cancer cell-lines." (PMID 24760019, 2014).